ELN (elastin)
Diseases named in the same sentence as ELN in open-access papers (continued):
Sharing a sentence is not in itself a finding about the gene and the disease.
cardiac hypertrophy (9 papers, 2012 to 2025). "Loss of compliance is associated with factors that occur during worsening of PH such as elastin and collagen reduction in proximal PAs and is associated with parameters of RV failure including hypertrophy and systolic dysfunction." (PMID 37187786, 2023). "The moderate elevation of the heart weight observed after SEP treatment resembles the cardiac hypertrophy induced by the elastin production stimulator minoxidil in male rats and mice." (PMID 36362244, 2022). "DD mice develop morphological changes in the aortic wall (thickening with disorganized elastin fibers) leading to chronic hypertension and cardiac hypertrophy." (PMID 22319452, 2012). "Increased collagen-1 deposition has been associated with increased myocardial stiffness and a decrease in the elastin to collagen ratio has been found in decompensated cardiac hypertrophy." (PMID 23099820, 2012). "However, other research indicated a positive correlation between ELN gene upregulation and cardiac hypertrophy in mice." (PMID 40861045, 2025). "It has been shown that ELN gene deletion induced cardiac hypertrophy in a mouse model may be related to NOX-mediated oxidative stress." (PMID 40861045, 2025). "RVOTO tissue samples were histologically analyzed for myocardial hypertrophy, fibrosis, elastin content, and active EndMT (immunohistochemical double-staining for endothelial and mesenchymal markers and transcription factors Slug/Snail) and compared to four healthy controls." (PMID 35084525, 2022). "LOXL2 catalyzes crosslinking of collagens and elastin and is a contributor to cardiac hypertrophy." (PMID 36159334, 2022). "Data from the present study suggests that increases of the fetal aortic collagen:elastin ratio may be increasing the workload of the fetal heart, contributing to the previously observed cardiac hypertrophy in OBF1 fetal hearts, as hemodynamics are a primary determinant of fetal cardiac development." (PMID 36054207, 2022).
Ehlers-Danlos syndrome (9 papers, 2012 to 2025). The Ehlers–Danlos syndromes (EDS) are a clinically and genetically heterogeneous group of heritable connective tissue disorders (HCTDs) characterized by joint hypermobility, skin hyperextensibility, and tissue fragility. "Dysregulation of H2S production is connected to connective tissue disorder in individuals with impaired collagen and elastin synthesis (e.g., Ehlers-Danlos syndrome) and patients with a deficiency of mitochondrial sulfur dioxygenase (ETHE1)." (PMID 23028699, 2012). "Ehlers-Danlos syndromes (EDS) are a group of rare heritable connective tissue disorders, characterised ‘by the abnormal formation and/or assembly of collagen, fibrillin and elastin in the body’ (page 1)." (PMID 39052631, 2024). "Ehlers Danlos Syndromes (EDS) are a heterogeneous group of hereditary connective tissue disorders characterized by the abnormal formation and/or assembly of collagen, fibrillin and elastin in the body." (PMID 34376220, 2021).
glaucoma (9 papers, 2008 to 2024). Increased pressure in the eyeball due to obstruction of the outflow of aqueous humor. "Aging or chronic exposure to ocular hypertension may result in elastin fragmentation and replacement by collagen that causes a stiffer mechanical response in the TM of the glaucoma eyes." (PMID 36294371, 2022). "These abnormalities in elastin may be related to the development and progression of glaucoma in patients with DH." (PMID 39457566, 2024). "Interestingly, regarding primary open-angle glaucoma, elastin and lysyl oxidase-like protein 2 has been suggested as candidate susceptibility genes." (PMID 18483563, 2008). "However, as one previous study reported a lack of association of polymorphisms in elastin with pseudo exfoliation syndrome and glaucoma, these results suggest that ELN may be associated with DH as vascular factor." (PMID 39457566, 2024). "Whether enhanced proteolytic activity of plasmin in glaucoma was associated with changes in ECM degradation was investigated by subjecting the retinal lysates to immunoblotting and probing with antibodies against extracellular proteins including collagen, elastin and laminin." (PMID 28827627, 2017). "In the ONH, the ECM usually provides a frame and resilience for the nerves, however, in glaucoma, the ECM is altered by basement membrane thickening along the lamina cribrosa beams and also changes in collagen and elastin fibres within the beams." (PMID 24800062, 2014).
melanoma (9 papers, 2010 to 2026). A malignant, usually aggressive tumor composed of atypical, neoplastic melanocytes. "The authors of this study, conducted in vitro on cell cultures of dermal human fibroblasts and melanoma cells, showed that lutein inhibits cell loss, membrane damage, and elastin expression and increases cell viability." (PMID 38338710, 2024). "This could explain the histopathological data underlining a strong correlation between elastin fragmentation and melanoma aggressiveness." (PMID 20959825, 2010). "VGVAPG increased the migration of melanoma cells and the generation of elastin-derived peptides, enhancing the expression of elastin-degrading MMP-2 and MMP-3 through binding to galectin-3 and EBP receptors." (PMID 35008401, 2022). "In LF cells, synoviocytes, and melanoma cell lines, elastin-derived peptides and/or VGVAPG peptides have been demonstrated to promote the synthesis and/or secretion of inflammatory markers such as IL-1 and IL-6." (PMID 36036007, 2022). "Here, we found that also the expression of LOX, LOXL1, and LOXL3 encoding proteins that crosslink ECM proteins (collagens and elastin) are increased in many melanoma cells and primary melanomas." (PMID 30701028, 2018). "In conclusion, our results show that elastin degradation products are important modulators of in vivo melanoma growth and invasion through Mcol-A (MMP-1) expression." (PMID 20959825, 2010). "Our data show that in vivo, EDPs are involved in melanoma growth and invasion and reinforced the concept of elastin fragmentation as a predictive factor." (PMID 20959825, 2010). "In melanoma, fragmentation of elastin was found to occur at the invasive front of the tumor." (PMID 35008401, 2022). "Intense fragmentation of elastin has been observed at the invasive front of melanoma and in vitro studies suggested that EDPs could participate to such a process in vivo by inducing proteolytic cascades." (PMID 20959825, 2010). "This important finding point out that elastin degradation, which occurs during melanoma development, is one of the events that could drive tumour growth." (PMID 20959825, 2010). "For instance, it has been shown that the incidence of metastases increased as melanoma reached the subepidermal and dermal layers, suggesting that elastin degradation could facilitate melanoma progression." (PMID 20959825, 2010). "Elastin peptides possess several biological activities and in vitro data suggest they could be involved in the early phase of melanoma growth." (PMID 20959825, 2010). "Moreover, our work demonstrates that elastin degradation could be an important predictive factor of evolution in melanoma." (PMID 20959825, 2010). "Consequently, we confirm and demonstrate that elastin degradation could be an important predictive factor of melanoma evolution." (PMID 20959825, 2010). "In addition, intense elastin fragmentation was detected at the in vivo invasive front of melanoma." (PMID 20959825, 2010). "In vitro assays using dermal fibroblasts, melanoma cells, and macrophages demonstrated that DHC enhanced fibroblast viability, collagen I/III and elastin production, antioxidant enzyme activity, and wound-healing capacity while reducing senescence markers." (PMID 41596671, 2026). "The expression of elastin, MMP-1, MMP-2, TIMP-1, and TIMP-2 was examined in skin fibroblasts and melanoma cells irradiated with UVA or UVB rays." (PMID 38338710, 2024).
ascending aortic aneurysms (8 papers, 2014 to 2023). "The study found the BAV samples were stiffer and thinnest with less elastin compared with both simple ascending aortic aneurysm and BA samples." (PMID 36732689, 2023). "Maladaptive upregulation of Thbs1 results in disruption of elastin-contractile units and dysregulation of actin cytoskeletal remodeling, contributing to the development of ascending aortic aneurysms in vivo." (PMID 35432454, 2022). "Human ascending aortic aneurysms characteristically exhibit cystic medial degeneration of the aortic wall encompassing elastin degeneration, proteoglycan accumulation and smooth muscle cell loss." (PMID 30276199, 2018).
chronic lung disease (8 papers, 2009 to 2025). According to the definitions of the American and British Thoracic Societies, including pulmonary functional tests, X-rays, and CT scans for items such as fibrosis, bronchiectasis, bullae, emphysema, nodular or lymphomatous abnormalities. "Excessive degradation of the elastin matrix underlies the loss of elastic interdependence and alveolar degeneration associated with chronic lung disease in adults." (PMID 19772569, 2009). "The role of MMP12 (macrophage metalloelastase), a proinflammatory enzyme that degrades matrix proteins such as elastin, which leads to tissue remodeling, has been found to be elevated in chronic lung diseases and inflammatory processes." (PMID 39996798, 2025). "As a result, we cannot confirm if the upregulation of ELN in the lungs of young adult lambs in response to chronic fetal hypoxia is due to thickening of the lung tissue, as in chronic lung disease and/or due to increased alveolarization/vascularization." (PMID 39882327, 2024). "There is disagreement in the literature as to collagen and elastin content, organization and crosslinking in human aging and chronic lung disease." (PMID 28837561, 2017). "Inhaled NO was also found to normalize excessive elastin deposition as found in chronic lung disease." (PMID 27581501, 2017). "Both elastin and the lysyl oxidase content are increased in infants with chronic lung disease of prematurity." (PMID 24661418, 2014).
dilatation (8 papers, 2015 to 2025). "The medial degeneration score was not significantly related to several enumerated outcomes of aneurysm disease, including media thickness, medial fraction of elastin, and number of SMC." (PMID 34162971, 2021). "In addition to its well-proved antimicrobial capabilities, doxycycline inhibits phorbol-12-myristate-13-acetate-mediated matrix metalloproteinase 8 (MMP-8) and MMP-9 in human endothelial cells, reducing elastin degradation and MMP activity in a model of aneurysmal disease." (PMID 35808704, 2022).
Hypercholesterolemia (8 papers, 2015 to 2025). An increased concentration of cholesterol in the blood. "It has been suggested that VSMC-mediated remodeling of structural extracellular matrix components such as collagen and elastin may lead to increased arterial stiffness, an indicator that is a traditional independent predictor of cardiovascular risk in patients with familial hypercholesterolemia." (PMID 38255840, 2024). "collagen disorganization, proteoglycan enrichment, and elastin fragmentation), lipid oxidation, and macrophage infiltration in ex vivo swine aortic valve tissue with familial hypercholesterolemia." (PMID 41210332, 2025). "The potential influence of hypercholesterolemia on characteristic experimental AAA histopathology was assessed by comparison of aortic medial elastin degradation, SMC depletion, mural leukocye accumulation, and neovessel formation between groups." (PMID 34680067, 2021). "Administration of an MMP-12 inhibitor (RXP470.1) protected hypercholesterolemia Apoe−/− mice from Ang II-induced AAA formation and rupture-related death, associated with diminished medial thinning and elastin fragmentation alongside increased collagen deposition." (PMID 38891996, 2024).
skin cancer (8 papers, 2019 to 2025). "This was attributed to the “umbrella effect”, where skin tumors block UV light penetration, reducing fluorescence from underlying collagen and elastin." (PMID 40149358, 2025). "Increased production of free radicals leads to accelerated skin aging associated with a decline in the amounts of collagen and elastin fibers, reduction in skin thickness, and formation of wrinkles, skin cancers or hyperpigmentation (melasma, freckles, age spots)." (PMID 37630991, 2023). "This oxidative stress accelerates matrix metalloproteinases (MMPs) production, (especially MMP1), leading to collagen and elastin degradation in human skin, implicating sunlight as a major factor in photoaging and even skin cancer." (PMID 40227287, 2025). "Excessive and repeated exposure to ultraviolet radiation, especially UVA induces oxidative stress, DNA damage, inflammation, and collagen and elastin degeneration, ultimately leads to skin photoaging, manifested by skin redness, coarse wrinkles, and pigmentation even skin cancer." (PMID 36499715, 2022). "Prolonged exposure to UV rays causes skin-aging symptoms, such as skin problems, spots, freckles, skin pigmentation, and skin diseases such as skin cancer, and is directly involved in the formation of wrinkles by damaging collagen and elastin, the collagen fibers in the skin." (PMID 33808279, 2021). "Accumulating evidences showed that UVB-induced ROS accumulation could impair skin integrity by altering ECM components as well as by decreasing collagen, elastin, and HA secretion and thereby facilitating wrinkle formation or skin cancer progression." (PMID 34890367, 2021).
Stroke (8 papers, 2007 to 2025). Sudden impairment of blood flow to a part of the brain due to occlusion or rupture of an artery to the brain. "Among these, three are likely monogenic causes of stroke (ELN, SCN5A, and VHL genes), two are considered risk factors (FV and ADAMTS13), two have conflicting interpretations (ACAD9 and ENG), and three are most likely benign (CBS, PMM2, and PKD1)." (PMID 40650005, 2025). "Kaplan–Meier curves of event-free survival showed a significant increased incidence of ipsilateral stroke in patients with plaques that had an elastin content lower than median (52 mg/g, P 0.009 using Log Rank Chi-square test)." (PMID 25803692, 2015). "Patients with plaque elastin levels lower than the median (52 mg/g) had increased post-operative incidence of ipsilateral stroke (P for trend 0.009 using Log Rank Chi-square test)." (PMID 25803692, 2015). "Apolipoprotein E (APOE) and elastin (ELN) are plausible candidate genes involved in the pathogenesis of stroke." (PMID 17672902, 2007). "The finding that patients with a low plaque content of elastin have an increased risk of developing an ipsilateral stroke during the follow-up could not be confirmed when excluding those five patients who suffered an ipsilateral stroke perioperatively, i.e. between 24 and 72 hours after CEA." (PMID 25803692, 2015).
Cirrhosis (7 papers, 2012 to 2023). A chronic disorder of the liver in which liver tissue becomes scarred and is partially replaced by regenerative nodules and fibrotic tissue resulting in loss of liver function. "Although early cirrhosis likely can regress, the heavily cross-linked collagen and elastin of late cirrhosis may be resistant to remodeling." (PMID 22534759, 2012). "Therefore, the progression of HF may alter liver stiffness through the binding of collagen and elastic fibers, and the increased matrix stiffness caused by the net accumulation of elastin may be responsible for the progression of advanced fibrosis to cirrhosis." (PMID 37152902, 2023). "In contrast, bridging fibrous septa of cirrhosis contained abundant collagen 1 and bundles of mature elastin." (PMID 34267266, 2021). "This has important implications in relation to the failure of ECM-degradation in the paucicellular elastin-rich scars that characterise advanced cirrhosis." (PMID 23259590, 2012). "In addition, Mmp-12 knock-out mice have both increased collagen and elastin deposition in a TAA model of cirrhosis." (PMID 23259590, 2012).
COVID-19 (7 papers, 2020 to 2025). A disease caused by infection with severe acute respiratory syndrome coronavirus 2. "Areas of fibrosing organizing pneumonia displayed an extensive loss of alveolar epithelium that correlated with elastin degradation in the COVID-19 lung parenchyma." (PMID 38397474, 2024). "Epithelial injury and elastin degradation in the alveolar walls of COVID-19 lungs were associated with abundant collagen deposition." (PMID 38397474, 2024). "In support of this association, collagen/elastin ratios showed increased collagen deposition in the lung parenchyma in advanced fibrotic regions, which displayed widespread alveolar epithelial disintegration in COVID-19 patients." (PMID 38397474, 2024). "The present study investigated the role of neutrophils in the damage to the structural integrity of ECM proteins, the inverse relation between elastin and collagen, and the accumulation of fibrotic abnormalities in the lungs of fatal COVID-19 patients." (PMID 38397474, 2024). "In parallel, elastin fibers in the perivascular regions also displayed extensive dispersal in COVID-19 patients." (PMID 38397474, 2024). "Quantitative measurements confirmed that the lengths of elastin fibers were significantly reduced in lungs of COVID-19 patients." (PMID 38397474, 2024). "To evaluate the relations between collagen and elastin in COVID-19 patients, we examined the expression of collagen and elastin fibers in the thin-alveolar walls of COVID-19-positive and control lungs." (PMID 38397474, 2024). "The densitometry analysis revealed a significant reduction in tropoelastin concentrations in COVID-19 lungs, supporting the morphometric analysis of elastin degradation in the COVID-19 lungs." (PMID 38397474, 2024). "The most notable result of our study was the overall degradation of elastin in the extracellular matrix of COVID-19 lungs." (PMID 38397474, 2024). "The collagen/elastin ratio was increased four-fold in the lung sections of COVID-19 patients compared to control lungs." (PMID 38397474, 2024). "However, the lung histopathologic or morphologic evaluation of elastin degradation and its consequences on lung abnormalities in COVID-19 patients are still unclear." (PMID 38397474, 2024). "In COVID-19 lungs, the elastin fibers exhibited extensive disintegration." (PMID 38397474, 2024). "Indeed, the degradation in connexins, elastin, and extracellular collagen by MMPs might be potentiated by the stiffer collagen rapid replacement, which could induce fibrosis and other COVID-19 problems." (PMID 36831321, 2023). "Due to its impact on quality of life, the most important of post-COVID-19’s long-term sequelae is PC19-PF, which exhibits fibroblast persistence and the massive deposition of collagen, elastin, and other extracellular matrix components." (PMID 40332501, 2025). "Dysregulated neutrophil activity and NETosis contribute to elastin degradation, ECM remodeling, and fibrotic changes in COVID-19." (PMID 38397474, 2024). "Degradation of extracellular collagen, elastin and connexins by MMP-9 are emphasized with rapid turnover of stiffer collagen, that could be an inducer of fibrosis and numerous complications in COVID-19." (PMID 36438922, 2022).
diverticulosis (7 papers, 2022 to 2025). "Even though the cause of the high incidence of diverticulosis in patients with WS remains unknown, many studies suggest that a defect of the elastin protein is responsible for this disease." (PMID 39099908, 2024). "Studies have indicated that alterations in connective tissue abnormalities, such as changes in the cross-linking of elastin (a crucial extracellular matrix protein that provides resilience and elasticity to tissues and organs), may predispose individuals to asymptomatic diverticulosis." (PMID 38419785, 2024). "In further exploration of the genetic basis of diverticulosis, research should delve into the genetic variations in extracellular matrix (ECM) components such as collagens, elastin, fibronectin, laminins, proteoglycans, tenascins, and decorin." (PMID 38004080, 2023).